EPHA2 (EPH receptor A2)
Diseases named in the same sentence as EPHA2 in open-access papers (continued):
Sharing a sentence is not in itself a finding about the gene and the disease.
astrocytoma (6 papers, 2008 to 2022). "The expression of astrocytoma-associated antigens (IL13Rα2, Fra-1, and EphA2) in particular stages of astrocytoma-derived cultures was assessed both at the mRNA and protein levels." (PMID 25788865, 2014). "Based on previously published data, astrocytoma-associated antigens (AAAs), such as Interleukin-13 Receptor α2 (IL13Rα2), Fos-Related Antigen 1 (Fra-1), and EphA2 receptor tyrosine kinase (EphA2) were selected." (PMID 25788865, 2014). "The purpose of our study was to estimate the value of astrocytoma-associated antigens (AAAs) - IL13Rα2, Fra-1, EphA2 - and the most common molecular aberrations typical for astrocytomas as potential markers to screen the status of tumour-derived cell cultures in vitro." (PMID 25788865, 2014). "Moreover, the original tumours were evaluated concerning astrocytoma-associated antigens expression (IL13Rα2, Fra-1 and EphA2) using the real-time PCR method." (PMID 25788865, 2014). "Based on the observations presented here, a Phase I clinical trial in the treatment of canine astrocytomas has begun utilizing IL-13RA2- and EphA2- targeted cytotoxins in combination." (PMID 24147065, 2013). "In malignant astrocytoma, we recently determined that knockdown of SULF2 resulted in decreased activity of multiple RTK signaling pathways including PDGFR-alpha, IGF1R-beta and EPHA2, three pathways known to be involved in astrocytoma growth and invasion." (PMID 22643827, 2012).
brain tumor (6 papers, 2014 to 2024). "The antigenic domains predicted to be expressed as class I peptides for CD8 functional response lie within the intracellular portion of the EphA2 protein predominantly, and this was consistent with our C170 and C172 brain tumor response results." (PMID 34599026, 2021). "Previous studies have established EphA2 as a brain tumor specific antigen that is useful for tumor-targeting as well as tumor imaging." (PMID 24346635, 2014). "Analysis of the cell surfaceome in pediatric and adult tumors revealed EphA3 as a prominent cell surface protein across various brain tumor subtypes, especially in the context of comparison to existing immunotherapeutic targets in clinical development EphA2, HER2, CD276, CD70, and EGFR." (PMID 39111833, 2024). "However, in several cancers (i.e., lung, prostate, breast, and brain tumors), EphA2 is robustly and highly expressed." (PMID 34760690, 2021). "We tested whether this was unique to this brain tumor model (CT2A brain tumors) or whether a similar activity occurred in an EphA2 (+) syngeneic peripheral sarcoma tumor model." (PMID 34599026, 2021). "As a trivalent vaccine targeting EphA2, HER2, and IL-13Rα2 in pediatric malignant gliomas and ependymomas revealed feasibility, tolerability, and efficacy pediatric brain tumors, combination of targeted antigens might be the future direction of the development of CAR T-cell therapy." (PMID 33673696, 2021).
ependymoma (6 papers, 2020 to 2023). A WHO grade II, slow growing tumor of children and young adults, usually located intraventricularly. "Trivalent CAR T cells targeting to HER2, IL13Rα2, and EphA2 demonstrated efficacy in xenograft ependymoma models." (PMID 35265074, 2022). "EphA2, IL13Rα2, HER2, and Survivin molecules are expressed specifically in ependymomas, and have been shown potentially target for CAR T cell therapy." (PMID 35265074, 2022). "Studies have demonstrated increased expression of EphA2, IL-13Rα2, HER2 and Survivin in ependymomas." (PMID 32903405, 2020). "CAR-T cells with trivalent targets to EPHA2, HER2 and IL13Rα2 did show efficacy in xenograft models of ependymomas." (PMID 32903405, 2020). "CAR-T EPHA2, HER2 and IL13Rα2 cells, alone or in combination with the CSF are effective against primary, metastatic, and recurrent Group 3 MB in mouse models (as well as ependymomas)." (PMID 37508458, 2023). "Similarly, EPHA2, another tyrosine kinase, and IL13Rα2 targets are expressed by MBs (and ependymomas), but not by the developing healthy brain." (PMID 37508458, 2023).
lymph node metastasis (6 papers, 2014 to 2024). "EPHA2 mutations have been associated with lymph node metastasis in CCA and targeting the phosphorylation of EPHA2 at Ser897 has shown effectiveness in inhibiting metastasis." (PMID 37444544, 2023). "Correlation analysis revealed a close association between EPHA2 mutations and lymph node metastasis in ICC." (PMID 37444544, 2023). "Additionally, ARID1A and EPHA2 mutations were associated with lymph node metastasis of ICC." (PMID 35070505, 2022). "Notably, a high expression level of EphA2 protein was significantly associated with the RCC TNM classification (P=0.001), the size of tumor (P=0.001) and the presence of lymph node metastasis (P=0.022), respectively." (PMID 25013485, 2014).
lymphoma (6 papers, 2021 to 2025). A malignant (clonal) proliferation of B- lymphocytes or T- lymphocytes which involves the lymph nodes, bone marrow and/or extranodal sites. "EphA2 is upregulated in malignant lymphomas and EphA2-positive metastatic solid tumors, and it is regarded as a target for CAR T cell therapy (NCT05631886 and NCT05631899)." (PMID 39835140, 2024).
malignant glioma (6 papers, 2007 to 2022). A grade III or grade IV glioma arising from the central nervous system. "In malignant gliomas, patients positive for EPHA2 and negative for EFNA1 protein exhibited the shortest survival compared to other patients." (PMID 25025847, 2014). "The patient's tumor expressed both EphA2 and IL-13Rα2, and in vitro stimulated PBMC demonstrated superior EphA2883–891 and IL-13Rα2345–353-specific CTL reactivity compared to PBMC samples from two other patients with progressing malignant glioma." (PMID 18093336, 2007). "Potent induction of CTL and presence EphA2-specific memory CD8+ T cells observed in the current study suggest that GAA-specific immunity may serve as one critical surveillance mechanism against recurrence and progression of malignant glioma." (PMID 18093336, 2007).
mammary adenocarcinoma (6 papers, 2011 to 2024). "EphA2 is known to enhance ErbB2-induced mammary adenocarcinoma." (PMID 33946495, 2021). "EphA2 physically and functionally interacts with ErbB2 to amplify Ras/mitogen-activated protein kinase (MAPK) and RhoA signaling in tumor cells, indicating that EphA2 cooperates with ErbB2/Neu to promote mammary adenocarcinoma tumorigenesis and metastatic progression." (PMID 25013485, 2014). "Targeted disruption of EphA2 also impaired normal mammary epithelial growth and branching morphogenesis, as well as tumor initiation and lung metastasis in the MMTV-Neu transgenic model of mammary adenocarcinoma." (PMID 21935409, 2011).
mesothelioma (6 papers, 2017 to 2025). A usually malignant and aggressive neoplasm of the mesothelium which is often associated with exposure to asbestos. "Here, we found that pEphA2 S897 levels were higher in mesothelioma cells than normal mesothelial cells and that EphA2 phosphorylation at S897 was sustained by progranulin stimulation in an ERK1/2-dependent manner." (PMID 36471440, 2022). "A separate study suggested that silencing EphA2 enhanced the sensitivity of lung tumors and malignant plural mesothelioma cells to LipoplatinTM treatment." (PMID 28624791, 2017). "Since we demonstrated that EphA2 phosphorylation at S897 mainly relies on ERK1/2, these data suggest that FAK, by controlling ERK1/2 activation, might indirectly sustain EphA2 phosphorylation at S897 in mesothelioma cells." (PMID 36471440, 2022). "To further decipher the contribution of EphA2 in modulating the progranulin axis in mesothelioma, we generated MSTO-211H and NCI-H2052 cells with genetic deletion of EphA2 by CRISPR/Cas9 technology and compared the ability of GRN- and EphA2-KO cells to migrate and invade through matrigel." (PMID 36471440, 2022). "EphA2 activation with the ligand ephrinA1 inhibits growth of MM indicating that ephrinA1-dependent EphA2 action has likely a tumor suppressive function in mesothelioma." (PMID 36471440, 2022). "Notably, as in MSTO-211H, EGFR inhibition attenuated the phosphorylation of EphA2 on S897 in NCI-H2052 cells as well, suggesting a modulation of EphA2 activity by EGFR in mesothelioma cells." (PMID 36471440, 2022). "The proteins that were unique to mesothelioma samples (cell line and PE samples) were MAGED4, PRAME, WT1, ACRBP, EPHA2 and SOX11." (PMID 39921204, 2025). "All mesothelioma cell lines showed EphA2 phosphorylation at S897 above the level of MeT-5A cells, with MSTO-211H cells showing the highest levels, while EphA2 S901 phosphorylation was only detectable in NCI-H2452 and MSTO-211H cells." (PMID 36471440, 2022). "Recently, we have demonstrated that in mesothelioma cells, EphA2 is not the major progranulin signaling receptor and progranulin action is instead mediated by EGFR and RYK, a co-receptor of the Wnt pathway." (PMID 36980592, 2023). "Progranulin and EphA2 are expressed in mesothelioma cells but their mechanisms of action are not well defined." (PMID 36471440, 2022). "Thus, we investigated the impact of EphA2 depletion on the activation of the AKT and MAPK pathways in mesothelioma cells." (PMID 36471440, 2022). "In addition, because EGFR modulates EphA2 phosphorylation at Ser897 in mesothelioma cells, we can also hypothesize that EGFR could promote RYK phosphorylation indirectly by modulating EphA2 activity." (PMID 36980592, 2023). "However, the contribution of EphA2 activation is not clearly defined in mesothelioma cells, where we identified by RTK arrays that progranulin promoted tyrosine-phosphorylation of EGFR and RYK." (PMID 36980592, 2023). "In addition, EphA2 is phosphorylated at S897 in mesothelioma cells but the relevance of this event is not clear at the moment." (PMID 36471440, 2022). "However, our results indicate that EphA2 is not the major functional receptor for progranulin in mesothelioma cells, where progranulin activates a complex signaling network including EGFR and RYK." (PMID 36471440, 2022). "Indeed, FAK inhibition had a strong inhibitory effect on ERK1/2 activation and abolished progranulin-dependent activation of ERK1/2 independently of EphA2, in both MSTO-211H and NCI-H2052 cells, demonstrating the role for FAK in mediating progranulin-dependent activation of MAPK in mesothelioma." (PMID 36471440, 2022). "All together, these results suggest that EphA2 is not the main mediator of progranulin action in mesothelioma cells and that the role of progranulin and EphA2 in mesothelioma is context dependent and might depend on the specific mesothelioma tumor subtype." (PMID 36471440, 2022).
mesothelioma (continued). "In summary, these data suggest that progranulin action in mesothelioma cells does not either rely on EphA2 activation or that mesothelioma cells might compensate for the lack of EphA2 by promoting progranulin-dependent AKT and ERK1/2 activation in an EphA2-independent manner." (PMID 36471440, 2022). "In addition, there are no data establishing whether the progranulin/EphA2 axis is tumorigenic for mesothelioma cells." (PMID 36471440, 2022). "However, the phenotypes of GRN- and EphA2-deleted cells considerably differed in their migratory, invasive and in vivo tumor formation ability, thereby suggesting that EphA2 might not be the major functional progranulin receptor in mesothelioma." (PMID 36471440, 2022).
ovarian tumors (6 papers, 2010 to 2025). "In our system, loss or reduction of EphA2 through interaction with YSA-functionalized nanogels may provide an enhanced effect over delivery of EGFR siRNA alone leading to a dual-targeting strategy for chemosensitization of ovarian tumors." (PMID 20064265, 2010). "More recently, miR-520d-3p mimetic was found to synergize with EphA2 siRNA to reduce ovarian tumor size and invasive capacity." (PMID 28289080, 2017). "SiRNA-mediated silencing of EphA2 has reduced ovarian tumor growth in mouse models." (PMID 28289080, 2017). "Notably, EphA2 siRNA when used in combination with chemotherapeutic drug paclitaxel was more effective in inhibiting growth of HeyA8 or SKOV3 orthotopic ovarian tumors in mice compared to treatment with the control siRNA and paclitaxel." (PMID 24495444, 2014). "Another approach using a combination therapy of EphA2 small interfering RNA (siRNA) with the chemotherapeutic drug paclitaxel was more effective in inhibiting growth of HeyA8 or SKOV3 orthotopic ovarian tumors in mice than was treatment with the control siRNA and paclitaxel." (PMID 22370972, 2013). "A combination of EphA2 and focal adhesion kinase (FAK) siRNA resulted in significant decrease in ovarian tumors and tumor microvessel density reduction compared to monotherapy." (PMID 24495444, 2014).
pancreatitis (6 papers, 2022 to 2025). Inflammation of the pancreas. "They identified and demonstrated that exosomal EPHA2 could be utilized as a biomarker in PC for distinguishing PC from pancreatitis patients and healthy subjects." (PMID 35408909, 2022). "Especially, EV EphA2 could accurately distinguish PC patients with I-II stage from healthy controls (AUC = 0.96) or pancreatitis (AUC = 0.93)." (PMID 35606727, 2022).
prostate adenocarcinoma (6 papers, 2011 to 2023). "PC3 human prostate adenocarcinoma cells are a well-established model for studying Eph–ephrin pharmacology as they naturally express a high level of EphA2, the most promising target in cancer within Eph receptors and ephrin ligands." (PMID 37895923, 2023). "PC3 human prostate adenocarcinoma cells are a well-established model for studying Eph–ephrin pharmacology as they naturally express a high level of EphA2, a promising target for new cancer therapies." (PMID 37895923, 2023). "EphA2 expression was shown to be elevated in prostatic intraepithelial neoplasia, the predecessor to prostatic adenocarcinoma, suggesting a potential function for EphA2 in the early phases of prostatic tumorigenesis." (PMID 36830852, 2023). "Importantly, EphA2 expression was increased in high-grade prostatic intraepithelial neoplasia, the precursor to prostatic adenocarcinoma, indicating a possible role for EphA2 in the early stages of prostatic carcinogenesis." (PMID 33430066, 2021). "We used PC3human prostate adenocarcinoma and HT29 human colon adenocarcinoma cells as amodel for their known ability to naturally express EphA2." (PMID 21479221, 2011). "UD acts as a protein-protein antagonist of EphA2 (a receptor kinase) by interfering its phosphorylation mediated by Ephrin-A1, without inhibiting the kinase domain of EphA2, and using a mechanism other than cytotoxicity or anti-proliferative effect in the PC3 human prostate adenocarcinoma cells." (PMID 28946708, 2017).
colon adenocarcinoma (5 papers, 2011 to 2024). "In the TCGA dataset, EPHB1 C61Y was found in a colon adenocarcinoma and, aligned in the same position of the protein consensus sequence, the corresponding EPHA2 C70R mutant was found in a renal papillary cell carcinoma." (PMID 38102712, 2023).
fibrosarcoma (5 papers, 2020 to 2025). A malignant mesenchymal fibroblastic neoplasm affecting the soft tissue and bone. "The [64Cu]Cu-NOTA-anti-EphA2-CD11b-BsAb radioimmunoconjugate was subsequently administered to HT1080-fibrosarcoma-bearing nude mice via tail vein injection." (PMID 40434019, 2025). "In vivo efficacy studies involved treatment of CT26 and MCA205 (a weakly immunogenic fibrosarcoma derived cell line) tumour bearing mice with the EphA2-PBD or EphA2-Tub conjugates, resulting in a large percentage of CRs." (PMID 36046842, 2022). "EphA2 is overexpressed in Ras-transformed cells and transgenic mice overexpressing Ras, suggesting EphA2 as a direct transcriptional target of rat sarcoma (Ras)–(rapidly accelerated fibrosarcoma) Raf–ERK signaling." (PMID 32811512, 2020). "HT-1080 (EphA2-expressing human fibrosarcoma) xenograft mice were intravenously administered [89Zr]Zr-EphA2 mAb (n = 6) for PET scanning, and [177Lu]Lu-EphA2 mAb (n = 12) to evaluate the biodistribution and specificity of uptake in HT-1080 xenografts in a blocking study." (PMID 39934299, 2025).
gastric adenocarcinoma (5 papers, 2019 to 2022). "On the contrary, in a large study that included 91 gastric adenocarcinoma samples, high EPHA2 protein expression was associated with advanced tumor stage, size, LN metastasis, TNM stage, and lymphovascular invasion." (PMID 34445116, 2021). "EPHA2 and its ligand Ephrin A1 are overexpressed in gastric adenocarcinoma and elevated EPHA2 expression is associated with poor survival." (PMID 32005975, 2020). "Among the 144 patients with gastric adenocarcinoma, 95 (66%) cases were identified as EphA2-high, and 49 (34%) were EphA2-low." (PMID 30833656, 2019).
malaria (5 papers, 2018 to 2022). Malaria is a serious and sometimes fatal disease caused by a parasite that commonly infects a certain type of mosquito which feeds on humans. "Collectively, this data suggests that although ephrin-A ligand upregulation and shedding are induced during the inflammatory immune response to malaria, the modulation and expression of the membrane-bound receptor, EphA2, is likely more of a critical factor influencing susceptibility to ECM." (PMID 31999807, 2020). "CD81 and EphA2 were expressed at higher levels in imHCs than in HC-04 cells, a cell line most commonly used for malaria sporozoite infection." (PMID 29370800, 2018). "imHCs expressed all major malaria sporozoite-associated receptors known to be essential for parasite entry and intracellular development in the liver, including TAPA-1 (CD81), EphA2 and SR-BI." (PMID 29370800, 2018). "It suggests that EphA2 may be a common hepatocyte receptor across rodent and human malaria." (PMID 36513700, 2022). "Eph family receptors, and specifically EphA2, have been described as host factors for a wide range of pathogens besides KSHV and RRV, including hepatitis C virus, Chlamydia trachomatis, Cryptococcus neoformans, malaria parasites, and as very recently reported EBV." (PMID 29432452, 2018).
oesophageal cancer (5 papers, 2017 to 2024). "When examining individual EphA genes like EphA2 and EphA10, significant up-regulation was observed in cases of esophageal carcinoma (ESCA) and cholangiocarcinoma (CHOL)." (PMID 38952552, 2024). "EFNA1 and its receptor EPHA2 were upregulated and linked to shorter survival in patients, and activation of the EFNA1/EPHA2 signalling pathway regulated the proliferation and metastasis of oesophageal cancer cells." (PMID 32732965, 2020). "Along these lines, ephrin receptor A2 (EphA2) has been argued to be the main entry receptor for EBV into epithelial cells, and the E6 gene product of HPV18 was found to up-regulate EphA2 on immortalized esophageal carcinoma cells." (PMID 38136285, 2023).
viral infection (5 papers, 2013 to 2025). "Predominant activation of clathrin and its association with EphA2 very early during virus infection with concomitant decrease overtime indicates that the process is rapid and occurs at the very initial stage of infection." (PMID 23874206, 2013). "We next determined the effect of EphA2 shRNA on KSHV latent gene expression in HFF cells since KSHV latency establishment in these cells represents successful virus infection." (PMID 23874206, 2013). "Considering that EphA2 is also the receptor for some other viruses such as hepatitis C virus (HCV) and that it is a signaling hub, our findings may be relevant to other viral diseases and to endocrine-associated oncogenesis." (PMID 28957431, 2017). "When cells were treated with 20 μM MG132, EPHA2 and ALCAM the protein levels in Ad5-infected cells remained comparable to those of mock-infected cells, whereas, surprisingly, PTPRF levels were decreased in MG132-treated cells, even without viral infection." (PMID 28631589, 2017).